TPRX1 (tetrapeptide repeat homeobox 1)
Description:
Transcription factor expressed after fertilization required for zygotic genome activation (ZGA), a critical event in early embryonic development during which the developmental control passes from maternally provided mRNAs to the expression of the zygotic genome after fertilization. Binds and activates expression of key ZGA marker genes, such as NANOGNB, ZSCAN4, DUXB, KLF5 and DPPA3. Binds to regulatory DNA sequences containing a 5'-TAATCC-3' sequence motif.
Synonyms: FLJ40321; TPRX
Gene: Protein-coding gene on chromosome 19 (47,801,232 to 47,819,051, reverse strand). Ensembl gene ENSG00000178928.
Subcellular location: Nucleus
Pathways (Reactome):
Developmental Biology: Zygotic genome activation (ZGA)
Genetic constraint (gnomAD): Loss-of-function variants: 0 observed, 1.23 expected, observed/expected ratio (o/e) 0, 90% interval 0 to 1.65. That is too few expected variants to judge how well the gene tolerates losing a copy. Missense variants: 506 observed, 482.26 expected, observed/expected ratio (o/e) 1.05, 90% interval 0.98 to 1.13. Synonymous variants: 249 observed, 210.85 expected, observed/expected ratio (o/e) 1.18, 90% interval 1.06 to 1.31.
Homologues: Orthologues: chimpanzee TPRX1 (88% identical), macaque TPRX1 (63% identical). Paralogues in human: TPRX2 (48% identical).
Diseases named in the same sentence as TPRX1 in open-access papers:
TPRX1 is named in the same sentence as 1 disease in open-access papers, as found by Europe PMC text mining. Sharing a sentence is not in itself a finding about the gene and the disease.
TPRX1 shares sentences with these, for which no sentence is quoted: cancer (1 paper).